HECTD4 (HECT domain E3 ubiquitin protein ligase 4)
Description:
E3 ubiquitin-protein ligase which accepts ubiquitin from an E2 ubiquitin-conjugating enzyme in the form of a thioester and then directly transfers the ubiquitin to targeted substrates.
Synonyms: C12orf51; KIAA0614; FLJ34154; C12ord51; HEEL; NEDSSCC; POTAGE
Gene: Protein-coding gene on chromosome 12 (112,160,188 to 112,382,439, reverse strand). Ensembl gene ENSG00000173064.
Subcellular location: Membrane
Subcellular location (Human Protein Atlas): Nuclear speckles; Vesicles; Nucleoplasm
Genetic constraint (gnomAD): Loss-of-function variants: 100 observed, 404.43 expected, observed/expected ratio (o/e) 0.25, 90% interval 0.21 to 0.29. The upper end of that interval is the gene's LOEUF score, 0.29, which puts it in group 1 of 6, group 1 being the genes least tolerant of losing a copy. Missense variants: 3,645 observed, 5,378.7 expected, observed/expected ratio (o/e) 0.68, 90% interval 0.66 to 0.7. Synonymous variants: 1,915 observed, 2,151.7 expected, observed/expected ratio (o/e) 0.89, 90% interval 0.86 to 0.92.
Homologues: Orthologues: chimpanzee HECTD4 (99% identical), macaque HECTD4 (99% identical), pig HECTD4 (98% identical), dog HECTD4 (98% identical), rabbit HECTD4 (97% identical), mouse Hectd4 (97% identical), rat Hectd4 (97% identical), tropical clawed frog hectd4 (88% identical), zebrafish HECTD4 (79% identical). Paralogues in human: HECTD1 (12% identical), TRIP12 (10% identical), HERC2 (7% identical), HUWE1 (7% identical), HECW1 (6% identical), HECW2 (5% identical), UBR5 (5% identical), HERC3 (4% identical), HERC4 (4% identical), ITCH (4% identical), WWP1 (4% identical), NEDD4L (4% identical), and 12 more.
Diseases named in the same sentence as HECTD4 in open-access papers:
HECTD4 is named in the same sentence as 36 diseases in open-access papers, as found by Europe PMC text mining. Sharing a sentence is not in itself a finding about the gene and the disease. The quoted sentences say what the papers report.
glioma (7 papers, 2022 to 2025). A benign or malignant brain and spinal cord tumor that arises from glial cells (astrocytes, oligodendrocytes, ependymal cells). "The circNEIL3 stabilizes IGF2BP3 via blocking HECTD4-mediated ubiquitination, thereby promoting the oncogenic progression of glioma." (PMID 37968257, 2023). "Furthermore, we found that the protein level of IGF2BP3 was dramatically increased, while its level of ubiquitination was obviously decreased, in HECTD4-knockdown GBM cells, indicating that HECTD4 acts as an E3 ubiquitin ligase to degrade IGF2BP3 via the ubiquitin–proteasome pathway in glioma." (PMID 35031058, 2022). "Consistent with our results, circNEIL3 binds to IGF2BP3 and inhibits the ubiquitination of IGF2BP3 by E3 ubiquitin ligase HECTD4, thereby inhibiting the degradation of IGF2BP3 by the proteasome and promoting the proliferation and metastasis of glioma cells." (PMID 37340423, 2023). "EWSR1 promotes glioma progression by cyclizing circNEIL3, thereby blocking HECTD4-mediated ubiquitination, stabilizing IGF2BP3, and promoting glioma progression." (PMID 37964279, 2023). "Meanwhile, we observed that circNEIL3 can bind to IGFB2P3 to block the interaction between IGF2BP3 and HECTD4 and induce the upregulation of IGF2BP3 in glioma." (PMID 35031058, 2022). "Unlike the findings in lung cancer, we first demonstrated HECTD4 as an E3 ubiquitin ligase that can induce ubiquitination of IGF2BP3 in glioma." (PMID 35031058, 2022). "For instance, the high expression of circNEIL3 in glioma cells was found to block the binding between IGF2BP3 and HECTD4, via the modulation of protein ubiquitination and degradation, as well as cellular immunosuppressive responses, thereby promoting malignant progression of glioma." (PMID 36139074, 2022).
diabetes (6 papers, 2015 to 2026). "Studies have found that HECTD4 polymorphism has a protective effect on the risk of diabetes in drinkers." (PMID 41554047, 2026). "Inherited genetic variants of HECTD4 are associated with neurological disease and increased risk for diabetes and hypertension." (PMID 40768362, 2025). "Similarly, both ATXN2 and HECTD4 are associated with diabetes mellitus, and we identified known MI regions uniquely associated with single MI in these genes." (PMID 38725839, 2024). "Consequently, we found that HECTD4 polymorphisms had a protective effect regarding diabetes risk among drinkers." (PMID 35713687, 2022). "We showed that the rs77768175 AA genotype, rs2074356 GG genotyp,e and rs11066280 TT genotype in HECTD4 were associated with significantly increased risks of diabetes (by 1.839, 1.746, and 1.723 in the HEXA group and by 1.719, 1.787, and 1.659 in the Ansan–Ansung group, respectively) in drinkers." (PMID 35713687, 2022). "Furthermore, we found that the rs77768175 AA genotype, rs2074356 GG genotype, and rs11066280 TT genotype in HECTD4 had increased risks of diabetes by alcohol consumption amounts (low, moderate, and high) in the HEXA group." (PMID 35713687, 2022). "However, no significant relation of HECTD4 variants to diabetes risk was observed among nondrinkers in the Ansan–Ansung cohort." (PMID 35713687, 2022). "As a result, we assessed the effects of the two THR-associated HECTD4 variants on diabetes-related traits, such as hyperglycemia, IFG, and DM, in the entire study group, as well as in male and female subjects, respectively." (PMID 26675016, 2015).
Hypertension (5 papers, 2017 to 2025). The presence of chronic increased pressure in the systemic arterial system. "In the previous GWASs, several variants of HECTD4 reported their association with various phenotypes including coffee consumption, alcohol consumption, high-density lipoprotein (HDL), glycemic traits, drinking behavior, SBP, DBP, and hypertension." (PMID 34828409, 2021). "Although there is no research about the role of HECTD4 in the development of hypertension, the ubiquitin system is known to be involved in the control of blood pressure." (PMID 34828409, 2021). "Although this locus was not significant in sex-stratified analysis, rs11066280 of HECTD4 showed a significant result in the EWAS of hypertension." (PMID 34828409, 2021).
type 2 diabetes (4 papers, 2015 to 2022). "Our findings provide additional insights into genetic variations of HECTD4 associated with alcohol consumption in the pathogenesis of type 2 diabetes." (PMID 35713687, 2022). "Unlike a previous report, the present study investigated the association between genetic variants in HECTD4 and type 2 diabetes according to alcohol consumption in two cross-sectional studies." (PMID 35713687, 2022). "In our study, we examined the potential effects of HECTD4 genetic variants on the prevalence of type 2 diabetes based on alcohol intake." (PMID 35713687, 2022). "Our results demonstrate that variants in the HECTD4 gene predispose patients to type 2 diabetes through alcohol consumption." (PMID 35713687, 2022). "Multiple logistic regression showed that statistically significant associations of HECTD4 gene polymorphisms with an increased risk of type 2 diabetes were found in drinkers." (PMID 35713687, 2022). "rs2074356 in HECTD4 was associated with prevalent type 2 diabetes and blood glucose level in a Korean population." (PMID 32722627, 2020). "Of these, wild-type HECTD4, believed to encode an E3 ubiqutin ligase-4, has been reported to increase risk of type-2 diabetes [PMID: 26675016]." (PMID 29632305, 2018). "The association between HECTD4 variants and type 2 diabetes was previously reported." (PMID 35713687, 2022). "Consequently, consistent with our results, the results of these studies suggested that the genetic markers of the HECTD4 gene have an impact on the risk of type 2 diabetes and that these markers showed remarkably consistent associations with multiple metabolic traits." (PMID 35713687, 2022). "Moreover, we investigated the association between HECTD4 polymorphisms and the risk of type 2 diabetes according to drinking status, and statistically significant associations of HECTD4 gene-polymorphisms with increased risk of type 2 diabetes were found in drinkers." (PMID 35713687, 2022). "While the mechanism by which the HECTD4 region may influence susceptibility to type 2 diabetes, beyond increasing an individual’s THR, is poorly understood, HECTD4 is known as a gene that is pleiotropic for obesity/adiposity and inflammation, which could contribute to this process." (PMID 26675016, 2015).
cholangiocarcinoma (3 papers, 2020 to 2022). A carcinoma that arises from the intrahepatic biliary tree (intrahepatic cholangiocarcinoma) or from the junction, or adjacent to the junction, of the right and left hepatic ducts (hilar cholangiocarcinoma). "Studies of cholangiocarcinoma reported that increased expression of HEIH promoted tumorigenesis and progression by modulating miR-98-5p/HECTD4 axis." (PMID 34689775, 2021).
Obesity (3 papers, 2015 to 2025). Accumulation of substantial excess body fat. "We also found that HECTD4 is positively associated with body fat percentage in UKB and BMI in AoU; an additional 18 of our FDR-significant genes are nominally associated (p < 0.05) with an obesity-related trait in AoU." (PMID 40912257, 2025). "For the next gene in this cluster, encoding probable E3 ubiquitin-protein ligase (HECTD4), no information about its function has been found, making it a promising target for obesity research." (PMID 33805313, 2021).
prostate carcinoma (3 papers, 2021 to 2023). A carcinoma that arises from epithelial cells of the prostate gland. "HECTD4 is an E3 ubiquitin ligase that is associated with androgen receptor promotion in prostate cancer cell lines." (PMID 34828409, 2021). "And TMEM116, HECTD4, MAPKAPK5 was reported to be associated with renal cell carcinoma, prostate cancer and colorectal cancer." (PMID 35096568, 2021). "In prostate cancer, overexpression of HECTD4 has been reported to result in a simultaneous decrease in both androgen receptor (AR) and MYC proteins, while knockdown of HECTD4 results in an increase in both AR and MYC proteins." (PMID 37272305, 2023). "However, reports that decreased HECTD4 in prostate cancer leads to increased AR and MYC proteins and that increased AR/MYC is oncogenic in OSCC suggest that loss‐of‐function mutations in HECTD4 are oncogenic and may be a cause of carcinogenesis in elderly nonsmokers." (PMID 37272305, 2023).
breast carcinoma (2 papers, 2025). "Moreover, lower HECTD4 expression in breast cancer is associated with reduced progression-free survival." (PMID 40768362, 2025). "A role for the ubiquitin ligase HECTD4 in cancer is supported by clinical databases indicating a correlation between reduced HECTD4 expression in breast cancer and an adverse progression-free survival." (PMID 40768362, 2025). "To support a potential role in cancer, we first explored clinical datasets, observing that both HECTD4 mRNA and protein expression are considerably reduced in primary and metastatic breast cancers, compared with normal breast tissue." (PMID 40768362, 2025). "To assess the effect of HECTD4 knockdown in an additional breast cancer cell line, we transduced MDA-MB-468 cells with either sh-scramble controls or shHECTD4 along with a luciferase reporter plasmid (Luciferase+ MDA-MB-468)." (PMID 40768362, 2025). "In breast cancer models, HECTD4 expression is induced as cells lose adherence to the matrix, and its depletion massively increases COX-2 expression, enhancing anchorage-independent proliferation and tumorigenesis." (PMID 40768362, 2025). "COX-2 knockdown within breast cancer cells abrogates the anchorage-independent survival benefit of HECTD4 suppression, consistent with a tumor cell-intrinsic role for COX-2 activity in metastasis initiation." (PMID 40768362, 2025). "Among histological subsets of breast cancer, HECTD4 expression is lowest in the most aggressive subtype, triple-negative breast cancer (TNBC), a proportion of which display allelic losses around the gene locus." (PMID 40768362, 2025). "In addition to breast cancer, HECTD4 expression is reduced in multiple other tumor types compared with corresponding normal tissues, including glioblastoma and esophageal cancers." (PMID 40768362, 2025). "Thus, even in the highly invasive MDA-MB-231 breast cancer cells, suppression of HECTD4 further enhances both primary and metastatic tumorigenesis." (PMID 40768362, 2025). "Our initial CRISPR-i screen scored HECTD4 as a suppressor of metastasis initiation by breast cancer patient-derived CTCs, and our follow-up analyses point to a critical effect in anchorage-independent cell proliferation, with COX-2 as a major degradation target." (PMID 40768362, 2025). "HECT family members have known targets implicated in breast cancer development and progression, but HECTD4 has remained uncharacterized, with no known function or other recognizable functional domain and noteworthy for its very large size (460 kD)." (PMID 40768362, 2025). "We show that HECTD4 specifically promotes the ubiquitination and degradation of COX-2, an effect that is most dramatic as breast cancer cells lose cell adhesion." (PMID 40768362, 2025). "The dramatic rise in COX-2 protein levels following depletion of HECTD4 under anchorage-independent culture is also seen in MDA-MB-468 cells as well as two other breast cancer cell lines BT-549 and HCC1143." (PMID 40768362, 2025). "Importantly, we also identified potential canine-specific oncogenic drivers, such as HECTD4 in malignant and NIPBL in epithelial-derived subtypes, that have been scarcely reported in human breast cancers, underscoring the significance in veterinary contexts." (PMID 41168812, 2025). "To further validate the inverse correlation between HECTD4 and COX-2 proteins, we analyzed a previously published proteomic dataset from 21 different human breast cancer cell lines, which confirmed the negative correlation between HECTD4 and COX-2 protein levels (N = 21, r = −0.426, P = 0.0541)." (PMID 40768362, 2025). "Although there has been no research to date on the role of HECTD4 in breast cancer, relevant studies have suggested that other similar genes in the HECT family, such as HECTD1 and HECTD3, play significant roles in breast cancer progression and treatment response." (PMID 41168812, 2025).
colorectal cancer (2 papers, 2021 to 2024). A primary or metastatic malignant neoplasm that affects the colon or rectum. "We explored whether LCD score and HECTD4 rs11066280 are etiological factors for colorectal cancer (CRC) and whether LCD score interacts with HECTD4 rs11066280 to modify CRC risk." (PMID 38523829, 2024).
esophageal cancer (2 papers, 2021 to 2025). A primary or metastatic malignant neoplasm involving the esophagus. "The rs2074356 of HECTD4 had previously been identified as a significant variant in the GWAS of waist circumference, esophageal cancer, blood urea nitrogen, and γ glutamyl-transferase level." (PMID 34828409, 2021).
Insulin resistance (2 papers, 2020 to 2024). Increased resistance towards insulin, that is, diminished effectiveness of insulin in reducing blood glucose levels. "In addition, LCD and HECT domain E3 ubiquitin protein ligase 4 (HECTD4) gene may be related to insulin resistance." (PMID 38523829, 2024).
Abdominal obesity (1 paper, 2016). Excessive fat around the stomach and abdomen. "Therefore, one possible mechanism is that C12orf51 polymorphisms (HECTD4) play a role in preventing abdominal obesity by participating in ubiquitination of a certain protein." (PMID 26891264, 2016).
alcoholism (1 paper, 2022). "In summary, we show that genetic variation in HECTD4 is associated with CVD risk in the presence and absence of alcoholism and that alcoholism significantly influences the pattern of DMR methylation associated with CVD in DNA prepared from whole blood." (PMID 35205218, 2022).
cardiomyopathy (1 paper, 2022). A disease of the heart muscle or myocardium proper. "The functional analysis of our data for two new loci (HECTD4 and MYL2) shows that they are associated with cardiomyopathy, suggesting that the association between AKT1 and the ApoA1 level has a direct connection to CVDs." (PMID 36140721, 2022). "Our GO and KEGG analyses revealed that HECTD4 and MYL2 are associated with cardiomyopathy, suggesting that the connection between AKT1 and the ApoA1 level has a direct connection to CVDs." (PMID 36140721, 2022). "Furthermore, GO and KEGG analyses revealed that HECTD4 and MYL2 are associated with cardiomyopathy, suggesting that the association between AKT1 and the ApoA1 level has a direct connection with CVDs." (PMID 36140721, 2022).
gastric cancer (1 paper, 2022). A primary or metastatic malignant neoplasm involving the stomach. "RUFY1 has been reported to promote disease progression in gastric cancer and HECTD4 was a favorable prognostic marker in head and neck cancer according to the Human Protein Atlas database." (PMID 35625741, 2022).
gout (1 paper, 2022). A condition characterized by painful swelling of the joints, which is caused by deposition of urate crystals. "The results revealed that the variants exhibited protective effects against developing gout, namely rs3733589 (SLC2A9), rs3775948 (SLC2A9), rs1014290 (SLC2A9), rs3109823 (ABCG2), rs2622604 (ABCG2), rs6532055 (ABCG2), rs72554040 (ABCG2), rs671 (ALDH2), rs78069066 (MAPKAPK5), and rs77768175 (HECTD4)." (PMID 36221101, 2022). "The involved genes were ABCG2, SLC2A9, PKD2, ZNF518B, ALDH2, HECTD4, and MAPKAPK5 in the phenotype of gout; and only gene SLC2A9 was found in the AH phenotype." (PMID 36221101, 2022).
Hepatic steatosis (1 paper, 2022). Steatosis is a term used to denote lipid accumulation within hepatocytes. "We next observed the impacts of HECTD4 knockdown on ethanol-induced hepatic steatosis." (PMID 35713687, 2022).
ischemic stroke (1 paper, 2025). A stroke disorder caused by obstruction of blood flow to the brain, due to thrombotic (local blood clot formation) or embolic (due to a blood clot or other material traveling from another site) event. "In ischemic stroke, MALT1 regulates GluN2B phosphorylation and calcium overload through its interaction with HECTD4, with downregulation reducing neuronal damage." (PMID 41567547, 2025).
oral cancer (1 paper, 2023). "First, the small number of cases in this study may have been the reason that the mutation in HECTD4 was the only gene mutation to show molecular biological features of oral cancer in older nonsmokers." (PMID 37272305, 2023).